ADAM10 (ADAM metallopeptidase domain 10)
Diseases named in the same sentence as ADAM10 in open-access papers (continued):
Sharing a sentence is not in itself a finding about the gene and the disease.
tumor (continued). "The metalloprotease ADAM10 is highly expressed in a range of tumour types, where it mediates activation of signalling pathways associated with tumour ‘stemness’, proliferation and angiogenesis." (PMID 35804938, 2022). "ADAM10 is highly expressed in a variety of solid tumors, including PCa, and promotes tumor deterioration." (PMID 35551177, 2022). "ADAM10 inhibits RhoA and Notch activation induced by exonucleosome treatment, and down-regulation of ADAM10 expression in TIMP-free fibroblasts reduces their tumor-promoting and metastatic potential in vivo." (PMID 36591235, 2022). "This cross-reactivity enables assessment of the relative binding of 8C7 to ADAM10 in tumour and normal tissue in mice with human tumour xenografts." (PMID 35804938, 2022). "We previously showed partial inhibition of tumour growth in mice using naked 8C7 alone, likely due to it inhibiting ADAM10-mediated Notch activation." (PMID 35804938, 2022). "The mean protein concentration of ADAM10 for the entire study group was higher in the surgical margin tissue than in the tumor tissue (249.34 vs. 228.82 pg/μg protein), but the results were not statistically significant (p = 0.22)." (PMID 36286024, 2022). "Tumor metastatic foci were observed in all the left lung tissues of the nude mice in the ADAM10 overexpression group, while only one of the six nude mice with ADAM10 knockdown had metastasis in the left lung tissues." (PMID 35551177, 2022). "In paediatric gliomas, the neuronal secretion of neuroligin-3 stimulates tumour growth, and its blockade via the inhibition of the ADAM10 sheddase markedly inhibits tumour growth." (PMID 36230865, 2022). "We previously reported the generation of a monoclonal antibody, 8C7, which preferentially recognises an active form of ADAM10 in human and mouse tumours." (PMID 35804938, 2022). "We thus conjugated cytotoxic drugs to 8C7 in order to preferentially bind and kill tumour cells that contain activated ADAM10." (PMID 35804938, 2022). "The selectivity of 8C7 for active ADAM10 in tumours is consistent with active ADAM10 having an open structure, allowing substrate and antibody access." (PMID 35804938, 2022). "Whereas the opposite results were observed in the primary tumors of DU145-shRNA2, suggesting that ADAM10 can promote tumor growth in vivo." (PMID 35551177, 2022). "Among the upregulated genes, ADAM10 (encodes a zinc-dependent protease) and TMEM165 (encodes a Golgi body transmembrane protein) have been reported to promote the invasion of tumor cells in multiple cancer types." (PMID 35816095, 2022). "We now provide insight explaining the specificity of our antibody (8C7) for active ADAM10, and show that it preferentially targets tumours when injected into mice." (PMID 35804938, 2022). "Overexpression of miR-140-3p in A549 cells up-regulated the anti-tumor activity of the selected drugs by acting on ADAM10." (PMID 36606198, 2022). "In parallel, miRNA-dependent down-regulation of ADAM9, ADAM10 and ADAM17 was associated with reduced tumor progression, inhibition of cell proliferation and invasion and chemotherapy sensitization of HCC cells." (PMID 33805340, 2021). "Next to the release of immunosuppressive factors, a hypoxic tumor microenvironment also impairs anti-cancer immunity through HIF-1α-mediated upregulation of ADAM10." (PMID 34055644, 2021). "E-cadherin is downregulated by MSCs in tumor cells through the activation of ADAM10 and inhibition of the epithelial-like tumor cell phenotype." (PMID 33472580, 2021). "The mRNA expression of ADAM17 and ADAM10 was much higher in TNBC as compared with non-tumor tissues." (PMID 34169001, 2021). "With TCGA dataset GEPIA validated that ADAM10 itself significantly increased in the tumor tissue than the normal (P<0.05)." (PMID 34345211, 2021). "Similar to other solid cancers, shedding of EGF-ligands and EGFR by ADAM10 and 17 are clearly relevant for tumor signaling in pancreatic cancer." (PMID 33578644, 2021).
tumor (continued). "The tumor-associated metzincin metalloproteinases ADAM10 and ADAM17 can cleave the PD-L1 ectodomain from the surface of tumor cells and extracellular vesicles, thus producing a soluble form of PD-L1 (sPD-L1), which can induce CD8+ T cell apoptosis." (PMID 34945784, 2021). "Increased expression of many Adamalysins including ADAM8, ADAM9, ADAM10, ADAM12 and ADAM17 was reported in HCC and associated with tumor progression." (PMID 33805340, 2021). "Taken together, the results indicate that MITF expression can promote the evasion of NK cell-driven tumor immunity through the proteolytic activity of ADAM10 on NKG2D ligands." (PMID 33789714, 2021). "Compared to ADAM17, ADAM10 expression was significantly lower in both tumor regions, with higher levels in TC compared to IC within MIBC (p = 0.004) and CIS (p = 0.007)." (PMID 33672843, 2021). "In vitro experiments where GBM cell lines were treated with an antibody to inhibit ADAM10 (Millipore #AB19026) found decreased tumor growth and migration." (PMID 32265938, 2020). "If they are, the process is consistent with the previously reported finding that GPNMB is cleaved by ADAM10 and secreted extracellularly in breast cancer cells." (PMID 32188902, 2020). "ADAM10 overexpression, reported in different tumor models, probably results from resident cancer epithelial cells, MSC and EV released into the extracellular space." (PMID 32668783, 2020). "Many different tumor types have identified ADAMs as potential biomarkers for disease or disease progression, the evidence for ADAM10 as biomarker is building and warrants larger-scale multi-center validation studies in order to be implemented in the clinic." (PMID 32265938, 2020). "Identifying patients who will benefit the most from ADAM10 inhibition therapy should be the priority, as well as applying ADAM10 inhibitors to prevent resistance of the tumor to standard treatments such as anti-CD30 or anti-HER2." (PMID 32265938, 2020). "This was validated through the use of the ADAM10 inhibitor (GI254023X) on tumor cell lines, where reduced release of Hsp90α was observed." (PMID 32265938, 2020). "Based on these data and considerations, ADAM10 is recognized as an attractive drug target to improve anti-tumor immunity, a topic extensively reviewed in recent papers." (PMID 32668783, 2020). "Since ADAM10 is also activated by thrombin and has been implicated in enhanced tumor cell invasiveness, it appears possible that in fact activated platelets contribute to tumor cell invasiveness by regulation of ADAM10 via thrombin/PAR-1 signaling." (PMID 32117229, 2020). "ADAM10 inhibitors were also able to preserve or enhance HL tumor cell ADCC triggered by anti-CD30 mAb iratumumab, thus showing pleiotropic beneficial effects." (PMID 32668783, 2020). "Another intriguing ADAM10 dependent mechanism involved in the immune evasion of tumor cells from NK cell reactivity has been recently described." (PMID 32269567, 2020). "In this context, we focused our attention on novel and more specific ADAM10 inhibitors with potential clinical value to balance immune escape by exosomal delivery to tumor tissues." (PMID 32668783, 2020). "Taken together, our results indicate that ADAM10 is implicated in MPM progression and mediates tumour cell invasiveness via N-cadherin cleavage." (PMID 30651596, 2019). "The key implication of ADAM10 in MPM progression in vivo is supported by the reduced tumour growth observed after the specific ADAM10 downregulation." (PMID 30651596, 2019). "Here, we demonstrated that HER‐2 ECD shedding was also associated with protein expression and alpha‐secretase activity of a disintegrin and metalloproteinase 10 (ADAM10) using tumor tissues and cell lines." (PMID 30661303, 2019).
tumor (continued). "A study found that hypoxia contributes to the tumor immune escape by increasing the tumor cell’s expression of the metalloproteinase ADAM10 in a hypoxia-inducible factor-1 (HIF-1α)-dependent manner, leading to the increased expression of PD-L1 on tumor cells." (PMID 31533363, 2019). "ADAM10 has a prominent role in several physiological and pathological pathways such as Notch signaling, embryonic development, tumor resistance to anticancerous agents or protection against Alzeihemer’s disease." (PMID 29630665, 2018). "Kaplan-Meier analysis revealed that T stage, regional lymph node metastasis, residual tumor, ADAM-10, ADAM-17, and ADAM-28 were associated with shorter time to tumor progression/recurrence (TTP)." (PMID 29776401, 2018). "Chronic or acute pharmacological stimulations of ADAM10 would engender many deleterious consequences, especially regarding its tumor-promoting activities." (PMID 29382156, 2018). "Testing of the RNA expression levels of the four upregulated genes in the tumour xenografts showed that decreased expression of the ADAM10 and IGF1R genes in the RPPH1 knockdown group." (PMID 29200969, 2017). "In gastric cancer tissue miR-448 and in tumor initiator cells of head and neck squamous cell carcinoma miR-494 were also identified as novel regulators of ADAM10." (PMID 28367112, 2017). "In glioma cells, upregulation of ADAM10 at the tumor edges was shown to result in increased soluble L1CAM, interacting with integrin receptors, activation of focal adhesion kinases, and focal complex turnover, all resulting in enhanced migration." (PMID 28260841, 2017). "In human non-small-cell lung cancer, overexpression of ADAM10 increased the migration and invasion potential of the tumor cells via the activation of the Notch 1 signaling pathway." (PMID 28260841, 2017). "Even though the ADAM10 protein was expressed in Crc regardless the presence of auto-Abs, the immature/non-functional isoform of ADAM10 was highly expressed in the tumor of anti-ADAM10-positive patients and was the isoform targeted by the auto-Abs." (PMID 27517630, 2016). "Metalloproteinases ADAM-10 and ADAM-17, which cleave membrane CXCL16 to generate soluble CXCL16, have also been linked to increased tumor burden." (PMID 27471636, 2016). "Since the auto-Abs raised in the patients specifically reacted with the ADAM10 pro-domain, it is unlikely that they act in inhibiting the ADAM10-sheddase activity in vivo and are contributing to tumor progression constraint." (PMID 27517630, 2016). "In our study, the unusual abundance of immature ADAM10 isoform expressed in the tumor of auto-Ab-positive patients seems to be responsible for the immunogenicity as suggested by the reactivity of patients’ IgG against the ADAM10 non-cleaved pro-domain." (PMID 27517630, 2016). "The expression of ADAM10 was determined using immunohistochemical analysis, which showed that ADAM10 staining was mainly located in the cytoplasm of tumor cells with varying staining intensity." (PMID 27602753, 2016). "In conclusion, our study demonstrate that miR-655-3p functions as tumor suppressor by directly targeting ADAM10 and indirectly regulating β-catenin pathway in HCC progression and metastasis." (PMID 27259866, 2016). "The expression of different ADAM10 isoforms, namely the 64 kDa mature/active isoform and the 98 kDa immature/inactive pro-protein, has been evaluated by WB on the available tumor tissues from Crc patients." (PMID 27517630, 2016). "An innovative feature of our study was the finding that decreased intensity of tumor-infiltrating lymphocytes (TILs) was strictly correlated with the increased number of ADAM-10 positive cancer cells in the primary tumor (P = 0.037)." (PMID 26266086, 2015). "Through these actions, ADAM10 is able to modulate the tumor microenvironment and the key processes involved in the progression of cancer, including cell proliferation, migration and angiogenesis." (PMID 25333745, 2015).
tumor (continued). "Mice model showed that SB treatment by oral gavage to xenograft tumors reduced tumor growth and prolonged the survival time of tumor-bearing mice by activation of miR-494-inhibiting Bmi1/ADAM10 expression." (PMID 26090866, 2015). "Spg-miR-494 enhanced the tumor growth; while sh-Bmi1+sh-ADAM10 co-knockdown inhibited the Spg-miR-494-induced tumor growth." (PMID 26090866, 2015). "The neuronal cell adhesion molecule L1 has also been identified as a β-catenin target gene and is preferentially expressed in tumor buds where it is co-regulated with ADAM10, a metalloprotease involved in cleaving and shedding L1s extracellular domain." (PMID 25806371, 2015). "A moderate to strong nuclear expression of ADAM10 was noted in tumor cells presenting a cytoplasmic expression of MUC1 while this was faint or absent when MUC1 expression was restricted to the membrane." (PMID 24504508, 2014). "In order to visualize the constitutive surface expression of ADAM10, we analyzed different tumor cell lines and T cell populations by flow cytometry using a mouse mAb raised against the extracellular part of human ADAM10 (clone AD214Y)." (PMID 24130797, 2013). "The connection between MET and tumor microenvironment is emphasized by the interplay with matrix proteases, such as ADAM-10, that modulate its activity." (PMID 22973229, 2012). "Similarly, ADAM10 overexpression in prostate cancer xenografts in mice facilitated tumour growth and metastasis, particularly in the lungs and lymph nodes, and was associated with elevated angiogenic markers CD31 and VEGF." (PMID 40427200, 2025). "Indeed, collagen fibrils were less evident in ADAM10 KO tumours by second-harmonic generation (SHG) microscopy." (PMID 41226720, 2025). "Other ADAM10-dependent signalling pathways are also implicated in GBM development, including Notch signalling, where ADAM10 mediates ligand-dependent Notch receptor activation, suggesting a more complex role in tumour development." (PMID 41226720, 2025). "Fibroblasts/mesenchymal cells in the TME may also contribute to the unexpected chondroid phenotype we observed in ADAM10 KO tumours." (PMID 41226720, 2025). "On the other hand, plasma sTIM-3 could be a marker of pro-tumor processes or cell types, such as ADAM10/17 activity in the TME." (PMID 39953623, 2025). "Vessel staining was significantly reduced in ADAM10 KO U251 tumours, compared to Wt." (PMID 41226720, 2025). "To shed more light on ADAM10 function, we investigated the effects of ADAM10 deletion, primarily on human U251MG GBM cells in vitro and in mouse xenografts, assessing associated changes in the secretome, proteome, and tumour phenotypes." (PMID 41226720, 2025). "Similarly, we identified that key GO functional gene sets were also correlated with ADAM10 expression in human tumours, including cell–cell interaction, Notch signalling, angiogenesis, ECM organisation, morphogenesis, and phosphate metabolism." (PMID 41226720, 2025). "LT4 and MN8 may have higher biological activity than GI254023X, another commercial drug, which also exerts anti-tumour effect through ADAM10." (PMID 39893499, 2025). "We therefore tested if conditioned medium from parental or ADAM10 KO U251 tumour cells could initiate differentiation of mouse MSCs in culture." (PMID 41226720, 2025). "Moreover, the expression of ADAM10 was reciprocally exclusive with some tumor immune checkpoint genes, such as VEGFB, LAG3, IL4, TNFRSF18, TNFRSF4, TNF receptor superfamily member 14 (TNFRSF14), CD27, CCL5, etc.." (PMID 39211038, 2024). "ADAM10 inhibition reduces xenograft growth by preventing NLGN3 release into the tumour microenvironment and could represent the basis of new therapeutic strategies." (PMID 38834748, 2024). "The transient or tumor-specific activity of ADAM10 or TACE/ADAM17 may play a key role because changing the mFKN/sFKN ratio modifies the signaling of the FKN/CX3CR1 axis to reveal anti- or pro-tumor effects." (PMID 38731899, 2024).
tumor (continued). "Furthermore, the ADAM‐10 SNP rs383902 and ADAM‐10 SNP rs653765 variants are correlated to larger tumour size of OSCC in specific population." (PMID 36946281, 2023). "In tumor mice with an overall therapy response, expression of genes encoding the proteases ADAM8, ADAM10, and ADAM17 was increased and might contribute to the immunosuppressive phenotype of GB and immune cells." (PMID 38139457, 2023). "As we identified ADAM10 as a key protease to induce CD44 dependent transcriptional upregulation of MMP14 and MMP2, inhibition of CD44 cleavage by ADAM10 might be a future translational approach to prevent tumor cell migration and invasion." (PMID 36876041, 2023). "In cancer, ADAM10 mediates tumor progression, metastasis and therapy resistance in several tumors." (PMID 37422628, 2023). "In some tumor types expression of ADAM10 and ADAM17 was increased compared to normal tissue." (PMID 37732732, 2023). "Since ADAM10 can enhance the anti-apoptotic ability of tumor cells by hydrolyzing Fas ligand." (PMID 35551177, 2022). "Next, HE staining was performed to detect whether ADAM10 could promote tumor metastasis in the left lung and lymph nodes of the nude mice." (PMID 35551177, 2022). "The authors concluded that the expression of this protein is significantly associated with the presence of lymph node and distant metastases and poor prognosis and proved that ADAM10 could be a predictor of tumour progression and prognosis." (PMID 35565436, 2022). "ADAM10 is a transmembrane metalloprotease that sheds a variety of cell surface proteins, including receptors and ligands that regulate a range of developmental processes which re-emerge during tumour development." (PMID 35804938, 2022). "In nude mice, ADAM10 accelerated growth of the primary tumor, decreased the level of ephrin-A5 in the tumor tissue, but increased the level of ephrin-A5 in the peripheral blood, accompanied with an increase in the expression of CD31 and VEGF (vascular endothelial growth factor) in the tissue." (PMID 35551177, 2022). "The concentration of ADAM10 was higher in the surgical margin than in the tumor (249.34 vs. 228.82 pg/μg protein), and the concentration of ADAM17 was higher in the tumor than in the margin (0.23 vs. 0.18 ng/μg protein), but results were not statistically significant." (PMID 36286024, 2022). "In addition, there was a relationship between ADAM10 concentrations and the histological grade of the tumour, as serum ADAM10 levels were elevated in G1 tumours when compared to G3 malignancies." (PMID 35565436, 2022). "In particular, active metalloproteases ADAM10/17 can release sPD-L1 from tumor tissue." (PMID 35184226, 2022). "It is concluded that ADAM10-mediated ephrin-A5 shedding promotes PCa metastasis via transforming the role of EphA3 from ligand-dependent tumor suppressor to ligand-independent promoter, and ephrin-A5 in the blood can be used as a new biomarker for PCa metastasis." (PMID 35551177, 2022). "EphA3, an essential regulatory target of ADAM10 through cleaving its primary ligand ephrin-A5, is a member of the receptor tyrosine kinase family, and has been reported to have dual biological effects in tumor progression." (PMID 35551177, 2022). "Mechanistic studies revealed that Tspan5 promoted cell migration and tumour metastasis by increasing the enzymatic maturation of ADAM10 and activating Notch signalling via the increase of the cleavage of the Notch1 receptor catalysed by the γ‐secretase complex." (PMID 33955149, 2021). "Both gene-targeting and drug-targeting ADAM10 reduced radiotherapy-induced pancreatic fibrosis and tissue tension, decreasing the migration and invasion of tumor cells, increasing the tumor sensitivity after radiation, and ultimately prolonging the survival of mice." (PMID 34067040, 2021). "Therefore, siRNAs targeting NLGN3/ADAM10 are promising for treating glioblastoma by modulating the interaction between neuronal cells and tumor cells." (PMID 34532286, 2021).